MSTN (myostatin)
Diseases named in the same sentence as MSTN in open-access papers (continued):
Sharing a sentence is not in itself a finding about the gene and the disease.
muscular atrophy (24 papers, 2013 to 2025). "Some authors observed an inverse relationship between age-related muscle loss and serum myostatin levels in the frail elderly, while skeletal muscle atrophy associated with lower myostatin levels has also been observed." (PMID 36359757, 2022). "Associations of myostatin to clinical and electrophysiological outcomes, muscular metabolism and muscular atrophy pathways were investigated." (PMID 35922829, 2022). "High myostatin concentration is associated with insulin resistance, which is in turn associated with muscular atrophy, resulting in poor exercise capacity and metabolic defects." (PMID 33898958, 2021). "NF-κB-mediated inflammation also leads to the upregulation of the ubiquitin ligases MuRF1 and atrogin-1 that are known to be involved in myostatin- or activin A-induced skeletal muscle atrophy by increasing protein degradation and inhibiting protein synthesis." (PMID 35380160, 2022). "Some studies have found that GCs can directly inhibit the function of muscle stem cells and lead to muscular atrophy by up-regulating myostatin." (PMID 36687405, 2022). "Our immunohistochemical analysis showed that the levels of pro-myostatin and/or the latent form of myostatin are elevated in the muscular atrophy model." (PMID 33495503, 2021). "Therefore, myostatin inactivation may prevent muscle loss in muscular atrophy." (PMID 31658768, 2019). "Inhibition of MAfxb in fasting mice with muscular atrophy led to decreased expression of myostatin and increased expression of the transcription factor MyoD which is implicated in muscle regeneration." (PMID 26856534, 2016). "In conclusion, we provide evidence for an inverse relationship between expression of microRNA-208b and its previously validated target myostatin in humans with severe skeletal muscle atrophy." (PMID 26603456, 2015). "We previously demonstrated that myostatin inhibition induced by overexpression of the myostatin pro-domain prevented muscular atrophy and normalized intracellular myostatin signaling in a mouse model of limb-girdle muscular dystrophy 1C (LGMD1C)." (PMID 23717655, 2013). "Akt represses expression of the muscular atrophy inducing E3-ubiquitin ligases MAFbx and MuRF1 through phosphorylation of FoxO transcription factors and conversely the repressive action of Akt on MAFbx and MuRF1 can be lifted by myostatin through SMAD2." (PMID 24963862, 2014). "Our results indicate that alterations in the protein turnover and myostatin levels could progressively impair the muscle mass maintenance and/or regeneration resulting in gradual muscular atrophy." (PMID 23840556, 2013). "During catabolic muscular atrophy, DEXA treatments have reported decreased mRNA expressions of SIRT1 and myostatin and muscular mass." (PMID 34066110, 2021). "We show that specific myostatin antagonism with the human antibody REGN1033 enhanced muscle mass and function in young and aged mice and had beneficial effects in models of skeletal muscle atrophy." (PMID 26457176, 2015). "However, only high-dose AM was able to improve gastrocnemius muscle atrophy in the model mice, with Coll, MSTN, and YY1 being phenotypes of skeletal muscle atrophy; FBXO32 and TRIM63 were indicators of protein synthesis." (PMID 39239655, 2024).
osteoporosis (21 papers, 2016 to 2025). A condition of reduced bone mass, with decreased cortical thickness and a decrease in the number and size of the trabeculae of cancellous bone (but normal chemical composition), resulting in increased fracture incidence. "Besides, some well-known genes are associated with muscle loss and osteoporosis concurrently, for example myostatin, proliferator-activated receptor gamma coactivator 1-α, myocyte enhancer factor-2 C, and methyltransferase-like 21C." (PMID 36820065, 2023). "This study aimed to explore the effects of 10-week weight-bearing ladder climbing exercise on ovariectomy (OVX)-induced osteoporosis and subsequent bone injury healing, and to investigate whether these effects are associated with the myostatin (MSTN) and Wnt/β-catenin pathways." (PMID 41514896, 2025). "The improvement in osteoporosis was evaluated via Micro-CT, biomechanical tests, RT-qPCR for mRNA detection, and Western blot for measuring protein levels of MSTN and Wnt/β-catenin pathway-related molecules at post-exercise and 21 days post-injury." (PMID 41514896, 2025). "This study represented the first efforts in measuring both precursor and mature forms of plasma myostatin simultaneously and testing their relationship with osteoporosis at distinct levels (muscle, circulation and bone) in human population." (PMID 29247983, 2018). "MSTN is shown to be a positive regulator of osteoclast differentiation, which is responsible for the resorption of aged bone and plays a role in bone degradation in arthritis and osteoporosis." (PMID 39340593, 2025). "Inhibiting MSTN may have therapeutic applications in promoting bone regeneration and healing in bone fractures, osteoporosis, rheumatoid arthritis, and osteoarthritis." (PMID 39340593, 2025). "In this study, ovariectomized (OVX) rats (a model of post-menopausal osteoporosis) exhibited increased serum and muscle myostatin levels relative to sham rats and had lower bone biomechanical and microarchitectural integrity, delayed fracture healing and elevated ActRIIB protein levels." (PMID 33854530, 2021). "Myokines, like irisin and myostatin, could be useful markers for the assessment of disorders of the muscle-bone unit and metabolic bone diseases or even therapeutic targets for the treatment of sarcopenia and osteoporosis." (PMID 36977715, 2023). "Myostatin has been an attractive target for treating musculoskeletal dysplasias associated with inferior muscle and bone function as seen in osteoporosis, OI, and DMD since myostatin regulates muscle metabolism and homeostasis." (PMID 33854530, 2021). "Our study indicates that myostatin is a promising candidate target for inhibiting RANKL-mediated osteoclastogenesis and might participate in therapy for osteoporosis, and that the Ccdc50 gene plays a significant role in the regulatory process." (PMID 33536903, 2020). "Experiments have confirmed that LIPUS can effectively reduce the MSTN content in serum and quadriceps muscle of ovariectomized rats, which suggests that LIPUS may improve osteoporosis and promote bone defect healing in ovariectomized rats by inhibiting the MSTN signaling pathway." (PMID 37593351, 2023). "Skeletal muscle secretes various myokines (e.g., myostatin, IL6, IGF-1, irisin) in an autocrine, paracrine, or endocrine manner to regulate the metabolic activities of bone cells in various ways and ultimately contribute to the pathogenesis of osteoporosis mechanisms." (PMID 36578964, 2022).
chronic heart failure (19 papers, 2012 to 2025). "In chronic heart failure, elevated myostatin production via the Smad-dependent pathway contributes to adverse cardiac remodelling." (PMID 41198895, 2025). "In particular, increased levels of cardiac derived myostatin act in an endocrine fashion on skeletal muscle to reduce muscle mass, in this way inducing a progressive skeletal muscle atrophy in patients with chronic heart failure." (PMID 36614282, 2023). "On the other hand, heart pathologies such as infarction, hypertrophy, and chronic heart failure increase myocardial expression of myostatin." (PMID 38136649, 2023). "Congestive heart failure is frequently accompanied by cardiac cachexia, and in rodent models and clinical trials, blocking MSTN appears to improve muscle size and strength significantly." (PMID 35565236, 2022). "In cases of chronic heart failure, circulating and local levels of MSTN, which play key roles in myocardial cachexia, are elevated." (PMID 35565236, 2022). "The relationship between myostatin levels in the circulatory system and patients suffering from chronic heart failure has been examined by various groups." (PMID 33802348, 2021). "Patients with chronic heart failure show an increase in myostatin mRNA and protein; however, they decrease with exercise, indicating a beneficial anti-catabolic effect in patients with chronic heart failure." (PMID 33019579, 2020). "This led to the conclusion that serum myostatin concentration could independently forecast survival outcomes in patients with congestive heart failure (CHF)." (PMID 39432214, 2024). "Patients with chronic heart failure (CHF) exhibit elevated levels of MSTN in their serum." (PMID 39432214, 2024). "Thus, the suppression of myostatin can be one of the factors of anti-catabolic effects of exercise training in chronic heart failure." (PMID 38136649, 2023). "There is good evidence showing that increased prolonged production of myostatin by the myocardium in the context of chronic heart failure may ultimately lead to the development of cardiac cachexia." (PMID 38136649, 2023). "Likewise, elevated myostatin levels are associated with progressive muscle wasting in chronic obstructive pulmonary disease (COPD), chronic heart failure (CHF), acquired immunodeficiency syndrome (AIDS), liver cirrhosis, ageing, and experimental cancer models." (PMID 31285507, 2019). "Myostatin mRNA expression is increased after infarction and exercise in the cardiac muscle, but remain unchanged in the canine model of dilated cardiomyopathy and chronic heart failure." (PMID 28077934, 2017). "Moreover, the elevated circulating myostatin has been demonstrated to be released from the myocardium of rats with chronic heart failure." (PMID 26998756, 2016). "Subjects with chronic heart failure had higher expression of myostatin in skeletal muscle and higher serum level of myostatin latent complex, after 12 weeks of exercise training, myostatin in skeletal muscle of chronic heart failure patient was significantly reduced." (PMID 22314403, 2013). "Apparently healthy individuals over the age of 55 had a median myostatin prodomain serum concentration of 3.9ng/ml (25th-75th percentiles, 2-7ng/ml) and we could not detect increased levels in patients with stable chronic heart failure or cancer related weight loss." (PMID 24260393, 2013). "In the discussed study, myostatin expression in the myocardium of patients with heavy chronic heart failure was elevated only in females, not males." (PMID 38136649, 2023).
chronic obstructive pulmonary disease (19 papers, 2013 to 2025). A chronic and progressive lung disorder characterized by the loss of elasticity of the bronchial tree and the air sacs, destruction of the air sacs wall, thickening of the bronchial wall, and mucous accumulation in the bronchial tree. "According to the literature, higher myostatin concentration was associated with worse general conditions, lower arterial blood oxygenation, and worse prognosis in patients with chronic obstructive pulmonary disease." (PMID 38672190, 2024). "For example, in‐hospital resistance training has been shown to favourably affect muscle function in patients with chronic obstructive pulmonary disease by influencing the anabolic‐catabolic balance and decreasing myostatin levels." (PMID 39400535, 2024). "In contrast, myostatin overexpression has been shown to be involved in muscle atrophy during different diseases such as chronic heart failure or chronic obstructive pulmonary disease." (PMID 35922829, 2022). "For example, the concentrations of myostatin were independently related to muscle wasting and inversely related to body skeletal muscle mass in patients with chronic obstructive pulmonary disease and predicted one-year mortality in patients on hemodialysis." (PMID 32443765, 2020). "Using the same ELISA kit as in our study, Ju and Chen revealed that the serum myostatin level was higher in patients with chronic obstructive pulmonary disease (COPD) than in the healthy control (11.85 ± 4.01 vs. 7.46 ± 2.21 ng/ml)." (PMID 28077934, 2017). "Myostatin levels increase with muscle atrophy due to unloading in mice and humans, and with severe muscle wasting in patients with cancer cachexia, chronic heart failure, chronic obstructive pulmonary disease (COPD), AIDS, and diabetes." (PMID 25221510, 2014). "For instance, Novartis tested bimagrumab (a monoclonal antibody directed against ActRIIB) both in IBM, which is characterized by increased Smad signaling in skeletal muscles, and chronic obstructive pulmonary disease (COPD), where myostatin upregulation in skeletal muscles is described." (PMID 35727341, 2022).
myocardial infarction (18 papers, 2016 to 2025). Gross necrosis of the myocardium, as a result of interruption of the blood supply to the area, as in coronary thrombosis. "Increased myocardial MSTN expression was observed after induced myocardial infarction in eight-week-old mice, and its effects, associated with protein degradation and skeletal muscle atrophy, persisted up to two months after myocardial infarction." (PMID 38542721, 2024). "Myostatin is upregulated under some pathological cardiac conditions, including myocardial infarction and heart failure." (PMID 41198895, 2025). "A prospectiveobservational study revealed a correlation between lower serum myostatin levelsand higher mortality rates among patients hospitalized for myocardial infarction(MI)." (PMID 39077334, 2024). "Myocardial infarction reduced serum myostatin concentration as compared to the healthy control group." (PMID 38136649, 2023). "A study of the effect of myostatin deficiency on alterations in left ventricular function after myocardial infarction showed that α-SMA activity was less intense in myostatin knockout than in wild-type mice, suggesting the possibility of fewer myofibroblasts." (PMID 37373277, 2023). "Data on the myostatin serum concentration after myocardial infarction are available in humans as well." (PMID 38136649, 2023). "Obviously, more data are needed on the relationship between myostatin and myocardial infarction in humans." (PMID 38136649, 2023). "MSTN is also highly expressed 12 h after myocardial infarction in human hearts and 10 min after ischemia in the hearts and blood of mice, where it contributed to skeletal muscle atrophy by upregulating atrogin and muscle RING-finger protein." (PMID 35806921, 2022). "Furthermore, serum myostatin levels were indicative ofmyocardial damage severity during acute myocardial infarction (AMI), akin to thecurrently used troponin I peak that estimates infarct size." (PMID 39077334, 2024). "In light of the data on the role of myostatin in heart physiology, it could be expected that myostatin might affect different parameters of the heart function after myocardial infarction." (PMID 38136649, 2023).
muscle disorders (15 papers, 2012 to 2025). "Myostatin has long been considered an attractive target for the treatment of these muscular diseases due to the remarkable phenotypes caused by genetic defects in myostatin, such as muscular hypertrophy and gain of strength." (PMID 33495503, 2021). "Most pharmacologic approaches that treat muscle disorders are ineffective, emphasizing the emergence of MSTN inhibition." (PMID 35807547, 2022). "For instance, the potent Myostatin inhibitor Follistatin affecting the Myostatin pathway has been shown to be clinically successful in treating muscular diseases." (PMID 28852138, 2017). "MSTN inhibitors offer a new therapeutic approach for various muscle disorders." (PMID 35457038, 2022). "These sex differences in MSTN and receptor gene expression may further account for the mixed outcomes of MSTN inhibition therapy for treating Duchenne Muscular Disease and other muscle disorders." (PMID 36314781, 2022). "Therefore, in this study, we aimed to design peptides that promote muscle proliferation and differentiation by targeting MSTN to develop a therapeutic alternative for the treatment of muscle disorders." (PMID 35457038, 2022). "In our study, the expression levels of different actors of the myostatin network were analyzed at messenger RNA (mRNA) and/or protein levels in the sera and/or biopsies of patients with different muscular diseases and in a mouse model of congenital myotubular myopathy." (PMID 29192144, 2017). "Indeed, numerous pharmaceutical companies are, in fact, currently working on developing myostatin inhibitors for the treatment of a variety of muscle disorders." (PMID 24504412, 2014). "Many researchers have focused on inhibiting myostatin for treating various muscle disorders." (PMID 22500226, 2012). "Of note, we do not provide an upper limit of normal, since nearly all muscle disorders would be expected to reduce the phase values, not increase them, with the exception, perhaps of myostatin mutations causing marked muscle hypertrophy as described in Whippets." (PMID 36619959, 2022). "Concerning the non-muscular diseases in which the main affected organ is not the muscle (such as cancer), a deep experimental evaluation of the therapeutic potential of the anti-myostatin approaches needs to be performed." (PMID 29192144, 2017). "So even if the choice of functional primary outcome was less than optimal, the results of the secondary outcomes do not suggest that myostatin inhibition was a viable treatment for any of the muscle disorders and conditions in clinical trial so far in our opinion." (PMID 33802348, 2021). "If no myostatin inhibition treatment has been able to improve severe (DMD), intermediate (sIBM), moderate (LGMD) muscle disorders or muscle wasting related to cancer or age, then this mode of treatment is likely not suited for treating any of these disorders and conditions." (PMID 33802348, 2021).
Hypertension (14 papers, 2012 to 2025). The presence of chronic increased pressure in the systemic arterial system. "Although these parts reveal an association between MSTN and hypertension, further mechanisms need to be uncovered." (PMID 37288303, 2023). "Furthermore, Serum myostatin levelsare independently associated with increased aortic stiffness in adolescents.These findings suggest that muscular factors contribute to the early onset ofsystemic hypertension and vascular aging." (PMID 39077334, 2024). "For this study we tested the response of a calorie-restricted Dietary Approaches to Stop Hypertension (DASH) diet on changes in myostatin, follistatin, and mystatin:follistatin ratio levels after 12 weeks in comparison to basline in adults aged 65 years and older." (PMID 35287731, 2022). "Thus, central obesity, serum TG and HDL cholesterol level were significantly related to serum myostatin level, after adjustment of age, gender, hypertension and impaired fasting glucose." (PMID 25254550, 2014). "Finally, genes and/or susceptibility loci on the long arm of chromosome 2 have been recently linked to blood pressure and hypertension by genome-wide association studies, such as STK39 at 2q24.3; PMS1 and MSTN, both at 2q32.2; DS2S2382 and DS2S338 at 2q35–q37." (PMID 22686481, 2012). "Myostatin (MSTN) is a TGF-superfamily member with anti-anabolic function; it is mainly produced by skeletal muscle and, in a smaller percentage, by smooth muscle, the myocardium, and the brain in response to several stimuli, including oxidative stress, inflammation, and hypertension." (PMID 35806921, 2022). "Serum myostatin was negatively related to central obesity, hypertriglyceridemia, and lower HDL cholesterol significantly, and not related to hypertension and impaired fasting glucose (Model 2)." (PMID 25254550, 2014).